EGFR (epidermal growth factor receptor)
Diseases named in the same sentence as EGFR in open-access papers (continued):
Sharing a sentence is not in itself a finding about the gene and the disease.
lung adenocarcinoma (3,048 papers, 1995 to 2026). A carcinoma that arises from the lung and is characterized by the presence of malignant glandular epithelial cells. "ER beta expression is associated with resistance to EGFR tyrosine kinase inhibitors (TKIs) in EGFR-mutant lung adenocarcinoma, indicating a potentially important interaction between ER and EGFR." (PMID 41597172, 2026). "Epidermal growth factor receptor (EGFR)-kinase domain duplication (KDD) represents an atypical mutation distinct from classical EGFR mutations in lung adenocarcinoma (LUAD)." (PMID 42041733, 2026). "To assess the dynamic regulation of LAPTM4B during the acquisition of drug resistance, we collected matched tumor tissues from six patients with histologically confirmed lung adenocarcinoma, all carrying EGFR 19Del mutations." (PMID 41362742, 2026). "We describe a rare presentation of metastatic EGFR-mutated lung adenocarcinoma complicated by NBTE, pulmonary embolism, splenic infarction, and acute coronary artery thrombosis." (PMID 41602399, 2026). "Research by Mezquita revealed that 90% of LFS patients with lung adenocarcinoma had driver gene mutations, mostly EGFR mutations, and the frequency of EGFR mutations was higher than that of the general lung adenocarcinoma population." (PMID 41498535, 2026). "Based on the study results, the therapeutic efficacy of gefitinib and erlotinib has been tested on lung adenocarcinoma patients with EGFR mutations, and both medications were found to show 100% efficacy of the tested patients." (PMID 41551443, 2026). "This study aimed to evaluate the clinicopathological, molecular, and survival characteristics of patients with metastatic EGFR-mutant lung adenocarcinoma according to RICTOR mutation status." (PMID 42080921, 2026). "We report the case of a 77-year-old woman with EGFR L858R-mutated lung adenocarcinoma (cT1cN3M1c stage IVB) who initiated first-line osimertinib 80 mg/day." (PMID 42220682, 2026). "This study is aimed at systematically identifying key genes associated with EGFR mutations and developing a molecular classification model in lung adenocarcinoma (LUAD) using integrative bioinformatics approaches." (PMID 42293334, 2026). "Current targeted therapies for LUSC harboring ALK, ROS1, or EGFR mutations are typically guided by protocols established for lung adenocarcinoma." (PMID 41868215, 2026). "The management of lung adenocarcinoma with brain metastases (BMs) is particularly challenging when BRAF-V600E mutations emerge as a resistance mechanism to EGFR tyrosine kinase inhibitors." (PMID 41727651, 2026). "EGFR Exon 19 deletions and exon 21 point mutations of EGFR are the most prevalent alterations in lung adenocarcinoma, and patients with these mutations derive substantial clinical benefit from EGFR tyrosine kinase inhibitors (TKIs)." (PMID 41626155, 2026). "Mechanistically, IL-1β acts on alveolar type 2 (AT2) cells, a cell-type of origin for lung adenocarcinoma, to enhance their progenitor stem cell capacity that is further exacerbated in the presence of an oncogenic EGFR mutation." (PMID 42001483, 2026). "We herein report a case of a 71-year-old female with bilateral multiple primary lung adenocarcinomas, in which separate lesions harbored an EGFR 19del mutation and a RET fusion gene, demonstrating intratumoral genetic heterogeneity." (PMID 41821900, 2026). "The overall EGFR mutation rate in Asian patients with lung adenocarcinoma is 51.4%, with a rate of 50.2% in China." (PMID 40347011, 2025). "Here, we present a case of stage IV lung adenocarcinoma with EGFR L858R mutation that developed peritoneal metastasis involving the small intestine, leading to intestinal obstruction and eventual death following resistance to osimertinib." (PMID 40432924, 2025).
lung adenocarcinoma (continued). "We present the case of a patient diagnosed with a lung adenocarcinoma harboring an EGFR del19/T790M/C797S triple mutation, who underwent treatment involving a combination of brigatinib and osimertinib." (PMID 40422529, 2025). "These subgroups were chosen for comparative analysis because ALK and ROS1 fusions are well‐validated fusion genes in lung adenocarcinoma, whereas EGFR mutations are a commonly validated driver gene primarily receiving targeted therapy." (PMID 40751559, 2025). "Its expression level is often increased in lung adenocarcinoma tissues with epidermal growth factor receptor (EGFR) mutations." (PMID 40860340, 2025). "The AUC of the combined model in predicting EGFR gene mutations in lung adenocarcinoma reached 0.827." (PMID 39962757, 2025). "Herein, we present a case of osimertinib-induced interstitial lung disease (ILD) in an 80-year-old woman with EGFR-mutated lung adenocarcinoma." (PMID 40538542, 2025). "To further investigate the role of RBM10 in brain metastases, we collected clinicopathological data from 23 lung adenocarcinoma patients with EGFR mutations." (PMID 40069781, 2025). "EGFR mutations are a key oncogenic alteration in lung adenocarcinoma, and inhibitors targeting this mutation have demonstrated promising therapeutic efficacy." (PMID 41357203, 2025). "In this study, we established and validated a comprehensive Clinical‐Radiomics‐Deep learning (CRD) model for predicting EGFR mutations in patients with lung adenocarcinoma." (PMID 41263395, 2025). "We collected 15 previously reported cases with detailed clinical data, all of which involved lung adenocarcinoma patients with the EGFR p.L833V/p.H835L compound mutation, predominantly from Asian populations." (PMID 40963567, 2025). "The PIONEER study revealed that 46.3% (671/1450) of Asian patients and 46.7% (346/741) of mainland Chinese patients with advanced lung adenocarcinoma were EGFR-sensitizing mutation positive and suitable for receiving EGFR-TKI therapy." (PMID 41326340, 2025). "The risk factors for brain metastases in NSCLC included lung adenocarcinoma, EGFR mutations, and prophylactic cranial irradiation (PCI); in SCLC brain metastasis, age and PCI were influential." (PMID 40650339, 2025). "Elevated SII is an independent biomarker for predicting ACM in individuals with stages IIIB–IV EGFR-mutated lung adenocarcinoma, with a stronger predictive value in male and older populations." (PMID 41268168, 2025). "We reported a case of initially diagnosed advanced lung adenocarcinoma co-harboring EGFR Ex19del mutation and MET de novo amplifications." (PMID 40034596, 2025). "Surprisingly, the mRNA levels of SHH and GLI1 were markedly upregulated in lung adenocarcinoma tissues with EGFR mutations (P < 0.0001 and P = 0.048, respectively)." (PMID 39721017, 2025). "In line with the data already available from previously published studies, EGFR mutation is a common finding in patients with lung adenocarcinoma, especially among women, and the exon 19 deletion is the most common variation." (PMID 40104451, 2025). "This case report describes a patient with stage IVa lung adenocarcinoma carrying an EGFR exon 19 deletion mutation." (PMID 40959071, 2025). "Here, we describe a patient diagnosed with stage IVB lung adenocarcinoma exhibiting uncommon EGFR mutations, G719S/S768I." (PMID 40277759, 2025). "A 44-year-old female, a non-smoker and with no comorbidities, was diagnosed with stage IIIB poorly differentiated lung adenocarcinoma in the left lower lobe, harbouring an activating EGFR ex19del mutation." (PMID 39972134, 2025).
lung adenocarcinoma (continued). "This ratio is consistent with the previous findings on the epidemiology of NSCLC druggable mutations, where almost half of patients with lung adenocarcinoma had EGFR or KRAS mutations." (PMID 40075579, 2025). "Here, we describe the first case of EGFR-mutated lung adenocarcinoma that recurred 14 years after curative lobectomy as a tumor-to-tumor metastasis to an intracranial meningioma." (PMID 41416296, 2025). "Among the 259 FFPE ADC tissue samples collected in our study, 198 (76.45%) were biopsies and 61 (23.55%) surgical; EGFR mutations were present in 121 (47%) lung adenocarcinomas." (PMID 40965349, 2025). "Among these, mutations in the epidermal growth factor receptor (EGFR) gene are the most prevalent, occurring in 45% of Asian patients and 20% of White patients with lung adenocarcinoma." (PMID 40740944, 2025). "In this paper, we report a case of advanced lung adenocarcinoma with EGFR-sensitive mutation that was transformed into small-cell lung cancer after EGFR TKIs treatment." (PMID 39995840, 2025). "Univariate analysis of the effects of EGFR 19, 21 mutation on pathological features of invasive lung adenocarcinoma." (PMID 41378298, 2025). "Herein, we present a case report of lung adenocarcinoma harboring the rare EGFR L747_A755delinsSKD mutation." (PMID 40308508, 2025). "First‐order variance features reflect intratumoral heterogeneity, a known imaging surrogate that has been associated with EGFR mutation status in lung adenocarcinoma; higher homogeneity (i.e. lower variance) has been correlated with EGFR‐mutant tumors." (PMID 41417019, 2025). "This study included 626 lung adenocarcinoma patients, with EGFR mutations found in 58.63% (367/626) and ALK gene rearrangements in 6.23% (39/626) of cases." (PMID 41378298, 2025). "For example, in lung adenocarcinomas, the EGFR mutation T90M becomes a driver only if the tumour cells have been previously selected by treatment with EGFR inhibitors." (PMID 40673272, 2025). "The results showed that CA-125 and CA-199 are better than CEAs at predicting worse outcomes in advanced lung adenocarcinoma, particularly in patients receiving targeted therapy for EGFR mutations." (PMID 40361443, 2025). "Herein, we present two cases of EGFR L861R‐mutated lung adenocarcinoma treated with afatinib and osimertinib to evaluate the clinical efficacy and tolerability of these targeted therapies." (PMID 41350121, 2025). "This study aims to evaluate the predictive value of spectral CT parameters, artificial intelligence (AI)-derived parameters, and clinical indicators for EGFR mutation in lung adenocarcinoma." (PMID 41244899, 2025). "Based on these findings, the authors concluded that first-line EGFR-TKI treatment was generally associated with favorable survival outcomes in patients with postoperative recurrent EGFR-mutated lung adenocarcinoma." (PMID 40723177, 2025). "The study’s findings will provide an evidence-based evaluation of the combination of CHM granules with chemotherapy for treating EGFR-mutated advanced lung adenocarcinoma with resistance to first-line EGFR-TKIs." (PMID 41257744, 2025). "This study evaluates CD73 expression in tumour and stromal cells of lung adenocarcinoma with EGFR genomic alteration and explores its association with clinical and molecular features." (PMID 40149368, 2025). "In our previous analysis of lung adenocarcinoma with EGFR Exon 20 insertion mutations, cases with EGFR amplification were significantly associated with high-grade histologic features." (PMID 40310364, 2025). "For tumor subtyping, it distinguishes lung adenocarcinoma (textural heterogeneity, AUC 0.80) from squamous cell carcinoma on CT and predicts EGFR mutations (75% accuracy) via ground-glass opacity patterns." (PMID 40361437, 2025).
lung adenocarcinoma (continued). "Imaging revealed bony destruction of the right fibular head, and further investigations with chest CT, PET/C, pathologic biopsy and genetic testing identified a primary lung adenocarcinoma with EGFR exon 19 deletion mutation." (PMID 39902235, 2025). "For patients with epidermal growth factor receptor (EGFR) -mutated lung adenocarcinoma who develop resistance to first-line EGFR-tyrosine kinase inhibitors (EGFR-TKIs), subsequent treatments typically involve a regimen that includes pemetrexed and platinum." (PMID 41257744, 2025). "Epidermal growth factor receptor (EGFR) mutations are detected in approximately 40%–50% of patients with lung adenocarcinoma in Asian populations and in around 10% of patients in Western populations." (PMID 41350121, 2025). "With advancements in molecularly targeted therapies, Epidermal growth factor receptor (EGFR) mutations have emerged as critical therapeutic targets in advanced lung adenocarcinoma." (PMID 40963567, 2025). "The aim of this study is to evaluate the efficacy and safety of CHM granules in combination with chemotherapy for patients with EGFR-mutated advanced lung adenocarcinoma following resistance to first-line EGFR-TKIs." (PMID 41257744, 2025). "EGFR T790M mutation is the most prevalent mechanism of acquired resistance in lung adenocarcinoma patients with EGFR sensitive mutation who have been treated with first‐ or second‐generation EGFR‐TKIs as their initial therapy, accounting for nearly 50%–60%." (PMID 41221800, 2025). "Recently, loss of an oncogenic driver mutation has been reported in a liver metastasis of an EGFR-driven lung adenocarcinoma following treatment with a neopeptide vaccine targeting the mutation." (PMID 41279090, 2025). "EGFR mutation is known to be the most common mutation type of lung adenocarcinoma, which is associated with specific clinical features." (PMID 40182027, 2025). "Age and brain metastasis emerged as the key factors in predicting EGFR 19Del and 21L858R mutation status in patients with lung adenocarcinoma." (PMID 41049833, 2025). "In this study, a patient with lung adenocarcinoma harboring an EGFR mutation exhibited primary resistance to the targeted EGFR inhibitor Osimertinib after 2 months of treatment." (PMID 39907312, 2025). "This study reports a case of EGFR L858R/T790M mutation-positive lung adenocarcinoma with LM and life-threatening intracranial hypertension that achieved marked clinical improvement through combined lumbar drainage and furmonertinib therapy." (PMID 40519289, 2025). "In this research, we analyzed the relationship between EGFR mutations and the clinicopathological features of lung adenocarcinoma to better understand the function of EGFR mutations in lung adenocarcinoma." (PMID 40182027, 2025). "The aims and objectives of the study are to estimate the prevalence of EGFR gene mutation in adenocarcinoma of the lung and to assess the clinical profile that correlates with EGFR gene status." (PMID 40104451, 2025). "This study reports two cases of advanced lung adenocarcinoma harboring the EGFR p.L833V/p.H835L compound mutation, both treated with furmonertinib." (PMID 40963567, 2025). "Univariate analysis of the effects of EGFR 19, 21 mutation on clinical features of invasive lung adenocarcinoma." (PMID 41378298, 2025). "In summary, our case report presented a lung adenocarcinoma patient who developed a novel METex14 skipping mutation (c.2888-23_2888-8del) after acquiring resistance to EGFR-TKIs treatment and exhibited clinical benefits from savolitinib therapy." (PMID 40129940, 2025).
lung adenocarcinoma (continued). "In advanced EGFR-mutant lung adenocarcinoma, high E-cadherin expression has been paradoxically linked to worse prognosis and increased brain metastasis, suggesting pro-survival or pro-metastatic functions under certain molecular contexts." (PMID 40943297, 2025). "Several studies have explored correlations between EGFR mutations in lung adenocarcinoma and specific clinical or imaging features." (PMID 41357203, 2025). "Here, we present a case of advanced lung adenocarcinoma, harboring a novel and rare METex14 skipping mutation, which potentially represents a new mechanism of resistance to EGFR-TKIs." (PMID 40129940, 2025). "Both logistic regression and decision tree models demonstrated value in predicting EGFR 19Del and 21L858R mutations in lung adenocarcinoma, each offering distinct methodological advantages." (PMID 41049833, 2025). "VGF, highly expressed in a subgroup of lung adenocarcinomas, has been linked to EGFR-TKI resistance and epithelial-to-mesenchymal transition." (PMID 40592939, 2025). "It involves the youngest patient among the previously reported five cases at only 40 years old with lung adenocarcinoma, and it is the first case among these with EGFR exon 19 deletion mutation." (PMID 39902235, 2025). "The mutation rate of EGFR in SqCLC is notably lower than in lung adenocarcinoma (LUAD), and SqCLC generally exhibits a poorer response to EGFR tyrosine kinase inhibitors (TKIs)." (PMID 41189942, 2025). "Molecular analysis revealed ALK-negative, ROS positive, epidermal growth factor receptor (EGFR) mutant (Exon 21 L858R point mutation), and positive PD-L1 30%, all supporting a lung adenocarcinoma diagnosis." (PMID 40134856, 2025). "This was also true when we limited the study to lung adenocarcinoma cell lines harboring only clinically acknowledged EGFR mutations (EGFR p.E756_A750del ELREA, L858R, T790M)." (PMID 39747003, 2025). "Epidermal growth factor receptor (EGFR)-mutated advanced adenocarcinoma of the lung is among the most prevalent mutation types." (PMID 41333366, 2025). "The integration of spectral CT and AI-derived quantitative parameters with clinical indicators demonstrates significant potential for noninvasive prediction of EGFR mutation in lung adenocarcinoma." (PMID 41244899, 2025). "For instance, EGFR mutations are very common in lung adenocarcinoma, with significant differences in prevalence in different regions, such as approximately 15% in Europe and up to 62% in Asia." (PMID 40347011, 2025). "This study investigates the relationship between the systemic immune-inflammation index (SII) and all-cause mortality (ACM) risk in individuals with stages IIIB–IV epidermal growth factor receptor (EGFR)-mutated lung adenocarcinoma." (PMID 41268168, 2025). "Furmonertinib appears to be an effective treatment for advanced lung adenocarcinoma with EGFR p.L833V/p.H835L compound mutations." (PMID 40963567, 2025). "The study presented the first documented case of lung adenocarcinoma harboring both EGFR G719A mutation and LMNA-NTRK1 fusion." (PMID 39988443, 2025). "A convenient and effective approach for detecting EGFR mutations in BAL-derived liquid biopsy samples from patients with lung adenocarcinoma has been reported." (PMID 41373464, 2025). "Here, we report a patient diagnosed with lung adenocarcinoma harboring EGFR 19Del L747-A755delinsSKD mutation with co-occurring T790M and trans-C797S mutations, who showed a positive response to combination therapy with first- and third-generation TKIs." (PMID 40308508, 2025). "The efficacy of osimertinib for EGFR‐mutated lung adenocarcinoma was previously shown to be excellent, with 80% of patients achieving a partial or complete response and median PFS increasing to 18.9 months." (PMID 40620186, 2025).